APOE (apolipoprotein E)
Diseases named in the same sentence as APOE in open-access papers (continued):
Sharing a sentence is not in itself a finding about the gene and the disease.
amyotrophic lateral sclerosis (29 papers, 2006 to 2025). Amyotrophic lateral sclerosis (ALS) is a neurodegenerative disease characterized by progressive muscular paralysis reflecting degeneration of motor neurons in the primary motor cortex, corticospinal tracts, brainstem and spinal cord. "APOE-ε4 carriership and cholesterol metabolism has additionally been implicated in the development amyotrophic lateral sclerosis (ALS) as well as multiple sclerosis (MS)." (PMID 39415269, 2024). "Here, we investigated whether the functionalization of avidin-nucleic-acid-nanoassembly (ANANAS) with apolipoprotein E (ApoE) would allow BBB passage in the SOD1G93A mouse model of amyotrophic lateral sclerosis." (PMID 36552768, 2022). "Although there are no similar studies in APOE ε4 carriers, the volume of the hypothalamus is affected in presymptomatic mutation carriers for amyotrophic lateral sclerosis, and in prodromal Huntington's disease, up to 15 years before predicted clinical diagnosis." (PMID 40356022, 2025).
psoriasis (29 papers, 2010 to 2025). An autoimmune condition characterized by red, well-delineated plaques with silvery scales that are usually on the extensor surfaces and scalp. "There is evidence suggesting that APOE polymorphisms also contribute to dermatological disease, since carriers of ε2 and ε4 alleles have been reported to show increased risk of psoriasis." (PMID 41465136, 2025). "Common genetic variants such as FUT2, UBE2L3, CDKAL1, SH2B3 and apolipoprotein E are more frequently found in psoriasis patients, having multiple functions that would explain their dual role in susceptibility to psoriasis and MS." (PMID 40003621, 2025). "Further reports have also implicated polymorphisms in the apolipoprotein E (ApoE) gene, a locus also strongly associated with AD, supplementary featuring the complex genetic architecture of psoriasis." (PMID 41465136, 2025). "APOE gene polymorphisms were further implicated in the pathogenesis of psoriasis, as APOE plays a role in the proliferation of T lymphocytes and protects against some infections in patients with psoriasis." (PMID 37569685, 2023). "The Saudi Arabia study evaluated the linkage between the APOE gene variants and psoriasis and found that frequencies of the ε2 and ε4 alleles and genotypes ε3/ε4 and ε3/ε2 were considerably higher in psoriasis patients in comparison to healthy controls." (PMID 34445769, 2021). "Evidence from a meta-analysis of seven studies suggested that the APOE polymorphisms were associated with the risk of psoriasis, especially E2 and E3 alleles." (PMID 26830841, 2016). "A meta-analysis of seven studies with 966 patients and 1,086 controls suggested that the APOE polymorphisms were assoated with the risk of psoriasis, especially E2 and E3 alleles." (PMID 24456740, 2014). "APOE is implicated in psoriasis by providing protection against some infections, as well as by modulating mitogen-activated T lymphocyte proliferation." (PMID 24782577, 2014). "Our results showed higher frequency of APOE ε2 allele and predominance of ε2/ε3 genotype in the psoriasis patients in comparison with matched controls suggesting that allele ε2 carriers are at a higher risk of developing psoriasis." (PMID 24782577, 2014). "But this relationship between APOE polymorphisms and the risk of psoriasis warrants further confirmation with large-size sample studies." (PMID 24782577, 2014). "Several studies have suggested an association between APOE alleles and genotypes with onset and severity of psoriasis." (PMID 24782577, 2014). "Shared genetic mechanisms for the risk of psoriasis, in particular severe psoriasis, and increased cardiovascular risk have been described, including apolipoprotein E gene polymorphism." (PMID 24278773, 2013). "Candidate-gene data indicate that APOE polymorphisms modulate risk in both conditions: ε2 and ε4 have been reported to increase psoriasis susceptibility (with ε3 protective), mirroring ε4-driven AD risk and suggesting allele-specific effects on lipid handling, vascular integrity, and inflammation." (PMID 41465136, 2025). "Other psoriasis-linked genes include APOE, CTLA4, DEFB4, GBP6, LCE, MCP1, VDR, and ZNF313." (PMID 37569685, 2023). "Several research studies indicated that high expression levels of APOE genes might be an independent risk factor for the occurrence of psoriasis." (PMID 33192461, 2020). "Apolipoprotein E (APOE) gene variants have been reported to influence psoriasis risk." (PMID 24782577, 2014). "In conclusion, our study showed that APOE polymorphisms are associated with psoriasis and allele ε2 is associated with increased susceptibility for psoriasis, whereas allele ε3 may be protective for psoriasis in Saudis." (PMID 24782577, 2014). "Therefore, in the present study, an attempt was made to investigate association of alleles and genotypes of APOE gene with psoriasis in Saudi patients." (PMID 24782577, 2014).
psoriasis (continued). "Recently a meta-analysis on association of APOE polymorphism with psoriasis indicated that APOE ε2 is associated with increased susceptibility to psoriasis and allele ε3 may decrease psoriasis risk." (PMID 24782577, 2014). "These unique properties of APOE ε2 may contribute to its role in the etiology of lipid associated diseases including psoriasis." (PMID 24782577, 2014). "Furthermore, ApoE gene polymorphisms are correlated with psoriasis, indicating that ApoE may have a pathogenic role in psoriasis." (PMID 37234169, 2023). "Larger, multi-ethnic investigations are needed to refine these associations and elucidate the molecular mechanisms through which ApoE influences both psoriasis and AD." (PMID 41465136, 2025). "The aim of this study was to evaluate the potential associations between serum concentrations of apolipoproteins (ApoA1, ApoA2, ApoB, ApoC1, ApoC3, ApoD, ApoE, ApoH, and ApoJ) and various clinical and biochemical markers in patients with psoriasis." (PMID 40137160, 2025). "While limited prior research has primarily focused on apolipoproteins such as ApoA1, ApoA2, ApoB, ApoC1, ApoC3, and ApoE in psoriasis, our study uniquely extends this scope by also evaluating ApoD, ApoH, and ApoJ in this patient population for the first time." (PMID 40137160, 2025). "In psoriasis, APOE expression levels showed positive correlations with the levels of 10 immune cell types and negative correlations with 6 immune cell types." (PMID 38273053, 2024). "No significant genetic correlation and causal relationship was found between lipidemic traits (HDL, LDL, TG, TC, apoA1, apoB, apoE) and psoriasis." (PMID 38550599, 2024). "The abundance of 6 immune cell types in psoriasis and leprosy positively correlated with the expression levels of APOE and CYP27A1." (PMID 38273053, 2024). "Polymorphisms of the apolipoprotein E gene (APOE) and the vascular endothelial growth factor gene (VEGF) have been evaluated as predictors of response to psoriasis patients treated with acitretin." (PMID 28146080, 2017). "Similar studies on different ethnic populations will be helpful in defining the role of APOE as a putative pharmacological target for psoriasis." (PMID 24782577, 2014). "The role of the APOE gene in psoriasis is also evident from the fact that in psoriatic skin there is the downregulation of APOE expression and the normalization of APOE levels precedes clinical improvement." (PMID 24782577, 2014). "A significantly lower frequency of ε3 allele was observed in Saudi psoriasis patients compared with matched controls (P = 0.0001) clearly indicating that APOE ε3 exerts protection against psoriasis." (PMID 24782577, 2014). "The role of the apoE gene in psoriasis was suggested, because in psoriatic skin there is the downregulation of ApoE expression and the normalization of ApoE levels precedes clinical improvement." (PMID 20706605, 2010). "Correlation analysis between APOE, CYP27A1, SOAT1, and immune cells revealed positive associations between the expression levels of APOE and CYP27A1 and the abundance of six immune cell types in both psoriasis and leprosy patients." (PMID 38273053, 2024). "We noted the appearance of apolipoprotein E (ApoE) in psoriasis and AD." (PMID 26966903, 2016). "These authors suggested that APOE-ε4 may influence disease severity in European patients with psoriasis." (PMID 24782577, 2014). "The implication of APOE ε4 in lipid metabolism and developing of immunologic responses to lipid antigens may contribute to psoriasis." (PMID 24782577, 2014). "On the basis of this immunomodulatory effect the APOE-ε4 has been attributed to psoriasis severity." (PMID 24782577, 2014). "Multiple studies have demonstrated that BA treatment significantly decreases VEGF, MCP-1 and TNF-α in different animal model such as in LPS-challenged ApoE mice, in a transgenic model of psoriasis, in an orthotopic nude mouse model of PaCa and in a murine sponge model." (PMID 24941000, 2014).
psoriasis (continued). "While ApoA1 and ApoB in psoriasis have been the primary focus of research due to their established roles in lipid metabolism and cardiovascular risk, other apolipoproteins, such as ApoA2, ApoC1, ApoC3, ApoD, ApoE, ApoH, and ApoJ, have not been widely studied in psoriasis." (PMID 40137160, 2025). "The ROC curves showed that APOE, CYP27A1, and SOAT1 had high AUC percentages in the GSE74481 dataset (reaching 99.2%, 91.5%, and 85.1%, respectively) and low AUC percentages in the psoriasis integrated dataset (reaching 15.0%, 15.0%, and 29.2%, respectively)." (PMID 38273053, 2024). "Among DEGs, APOE, CYP27A1, and SOAT1 confirmed as critical mutually exclusive genes, exhibiting opposite expression patterns in psoriasis and leprosy." (PMID 38273053, 2024). "In GSE66511 dataset, APOE, CYP27A1, FADS1, and SOAT1 were also significantly downregulated in psoriasis." (PMID 38273053, 2024). "Four hub genes APOE, CYP27A1, FADS1 and SOAT1 were downregulated in psoriasis, while were upregulated in leprosy." (PMID 38273053, 2024). "Box plots showed APOE, CYP27A1, and SOAT1 was upregulated in leprosy tissues, whereas their expression was downregulated in psoriasis tissues." (PMID 38273053, 2024). "In the GSE54456 dataset, APOE, CYP27A1, FADS1, and SOAT1 showed lower expression levels in psoriasis compared to the control group." (PMID 38273053, 2024). "Our data suggest that in ApoE−/− mice, TPA-induced psoriasis-like skin lesions lead to both local and systemic inflammation, but despite these effects, we found no alteration in atherosclerotic plaque development." (PMID 27401543, 2016). "Regarding lipidemic traits, we did not observe any significant genetic correlation with psoriasis (apoA1: rg=-0.03, p=0.261; apoB: rg=-0.02, p=0.615; apoE: rg=0.09, p=0.721; HDL: rg-0.05, p=0.077; LDL: rg=-0.04, p=0.344; TC: rg=0.08, p=0.164; TG: rg=0.06, p=0.053)." (PMID 38550599, 2024). "However, no independent locus was identified between apoE and psoriasis." (PMID 38550599, 2024).
Senile plaques (29 papers, 2006 to 2025). Senile plaques are extracellular deposits of amyloid in the gray matter of the brain. "In both AD patients and cognitively normal individuals, the APOE‐ε4 allele promotes the deposition of senile plaques." (PMID 36786148, 2023). "APOE colocalizes with senile plaques and microglia, suggesting a role for APOE in AD-associated innate immune response." (PMID 36372924, 2023). "It is of interest that α1AT, which is a serpin with known associations to AD in blood, CSF and senile plaques also correlated with the APOE ε4 allele, however the specific physiological role of α1AT in tissues is not well elucidated." (PMID 35081972, 2022). "In 1994, at least 35 protein components had been found to be associated with senile plaques, including apolipoprotein E (apoE), clusterin, vitronectin, coagulation factors, heat shock proteins, proteases and protease inhibitors." (PMID 34454574, 2021). "Apolipoprotein E (apoE) is associated with Aβ in senile plaques and it is also able to bind soluble Aβ peptide with high avidity." (PMID 32033502, 2020). "Almost all of the LMW CT fragments were found in the SDS fraction, confirming that these ApoE fragments are insoluble and therefore likely to be at least partially aggregated or associated with senile plaques." (PMID 21297948, 2011). "We reasoned that if ApoE isoforms differentially interact with Aβ in senile plaques, we may be able to detect, using advanced imaging techniques that are sensitive to protein conformation, distinct conformational patterns of ApoE3 and ApoE4, when associated with senile plaques." (PMID 21297948, 2011). "A study shows that APOE genotypes affect the formation of senile plaques due to abnormal deposition of Aβ, and also lead to development of cerebral amyloid angiopathy (CAA)." (PMID 36372924, 2023). "α1ACT is more highly expressed in the brains of AD patients and is a component of senile plaques, as is ApoE." (PMID 35081972, 2022). "APOE2, APOE3, and APOE4 proteins can each directly bind with Aβ, forming APOE/Aβ complexes that alter Aβ clearance, aggregation, and the formation of senile plaques." (PMID 32269835, 2019). "Co-localization of Aβ, APOE and LRPAP1 on senile plaques suggests its involvement in the clearance of APOE/Aβ complex." (PMID 29551980, 2018). "We applied a novel application of FLIM-FRET to in situ measurement and quantification of protein interactions to explore isoform specific differences in Aβ-ApoE interaction and ApoE tertiary conformation in senile plaques in human Alzheimer brain." (PMID 21297948, 2011). "Moreover, senile plaques has been shown to be more abundant in APOE ε4 carriers (40.7%), particularly patients aged between 50 to 59 years." (PMID 36372924, 2023). "Interestingly, senile plaques and drusen have been shown to have many common constituents, including Aβ, apolipoprotein E (APOE), and complement immune components." (PMID 31568508, 2019). "It was also shown in vitro that the carboxyl-terminus of ApoE could, itself, form amyloid-like fibrils, which were congo-red positive and are present in senile plaques, further emphasizing its role as a pathological chaperone." (PMID 23663404, 2013). "AD TREM2 mutants may therefore enhance Aβ deposition during the early stage of AD while leading to a reduction in APOE production by microglia and decreased APOE levels in senile plaques suggesting that TREM2 may have protective functions early during amyloidogenesis." (PMID 31649511, 2019). "Apolipoprotein E (ApoE), the ligand of LRP1, is involved in senile plaques in AD brains, implicating a role for LRP1 in the accumulation of Aβ." (PMID 35359573, 2022). "Due to the limited number of patients with the APOE ε4/ε4 genotype, this study does not reveal whether a specific APOE genotype is associated with either a higher probability of having senile plaques in TLE or with a shift in the age of onset for senile plaque formation." (PMID 22502767, 2012).
Senile plaques (continued). "In AD patients, APOE4 enhances Aβ deposition, where 40.7% of middle-aged APOE ε4 carriers featured senile plaques, compared to 8.2% non-carriers identified with senile plaques." (PMID 32677986, 2020). "It has been demonstrated that ApoE is codeposited in senile plaques in brains of patients with AD and ApoE4 carriers present a higher Aβ deposition in the form of senile plaques than noncarriers." (PMID 24734229, 2014). "Moreover, it is known that apoE binds to the lipoprotein receptor-related protein 1 (LRP1) receptor that is involved in active outward transport of Aβ across the blood-brain barrier and is frequently found around senile plaques." (PMID 28826183, 2017).
cardiac hypertrophy (27 papers, 2010 to 2025). "Therefore, cardiac hypertrophy can be considered a cause of cardiac dysfunction in apolipoprotein E-knockout mice." (PMID 34394711, 2021). "To explore the origin of CD34-derived fibroblasts in cardiac hypertrophy, we established chimeric mice by transplanting bone marrow cells from wild-type ApoE-/- mice into irradiated Cd34-CreERT2;Rosa26-tdTomato-ApoE-/- mice." (PMID 39198543, 2024). "For example, it has been shown that supplementation of propionate attenuated cardiac hypertrophy and fibrosis in Ang-II-infused wild-type and ApoE knockout mice by reducing splenic T cells." (PMID 36438501, 2022). "Others have demonstrated that aged ApoE KO mice generate cardiac hypertrophy under these conditions." (PMID 31575906, 2019). "LVAWd and LVPWd increased significantly in ApoE−/− mice plus high-dose PM2.5 indicted that ApoE−/− mice have cardiac hypertrophy induced by increased collagen deposition." (PMID 27187431, 2016). "In studies with apoE-/- mice in our laboratory, we regularly evaluate cardiac hypertrophy, which can be determined by measuring the cardiac weight-to-body weight ratio." (PMID 22330242, 2012). "Histological analysis of hematoxylin- and eosin-stained heart sections confirmed that two months of pressure overload had induced cardiac hypertrophy with dilation in ApoE-/- mice compared to sham-operated control mice (left vs. right panel)." (PMID 21711241, 2011). "Interestingly, only the old apoE-/- mice developed ventricular hypertrophy during aging, demonstrated by increased left ventricular mass and left ventricular wall thickness." (PMID 34816004, 2021). "In apoE-/- mice fed a normal diet, the cardiac weight has been reported as normal at different ages in several studies, but others have observed myocardial hypertrophy in adult and aged animals." (PMID 22330242, 2012). "On a Western-type diet, apoE-/- mice show cardiac hypertrophy that is worsened with aging." (PMID 22330242, 2012). "Therefore, our current study additionally demonstrated that KMUP-1 treatment may diminish cardiac hypertrophy in ApoE-KO mice fed with HFD." (PMID 41194853, 2025). "Importantly, the cardiac hypertrophy in response to the aortic coarctation-induced pressure overload is higher in apoE-/- mice than in C57 mice, leading to the hypothesis that apolipoprotein E may play an important role in modulating cardiac hypertrophy, even in wild-type mice." (PMID 22330242, 2012). "These processes may account for reduced cardiac hypertrophy and fibrosis we observed in MSC-Exos treated diabetic ApoE KO mice." (PMID 38390337, 2024). "The NF-κB inhibitor preserved lysosomal activity and suppressed cardiac dysfunction in apolipoprotein E-knockout mice fed a high-fat diet independent of changes in cardiac fibrosis and hypertrophy in this model." (PMID 34394711, 2021). "Mouse heart weight to tibial length ratio was increased under HFD, and histological analysis by H&E and Masson staining of cardiac sections showed disordered cardiac muscle fibers and increased myocardial fibrosis in ApoE-HFD heart, suggesting cardiac hypertrophy and remodeling." (PMID 27087279, 2016).